CD44 (CD44 molecule (IN blood group))
Diseases named in the same sentence as CD44 in open-access papers (continued):
Sharing a sentence is not in itself a finding about the gene and the disease.
breast carcinoma (continued). "Furthermore, the downregulation in the expression of HA and its receptor CD44 which is directly associated with the migration and matrix-associated invasion of breast cancer cells was also observed." (PMID 25140302, 2014). "Thus, our findings provide new insights into the mechanism underlying CD44 up-regulation in breast cancers and potential therapeutic strategy against breast cancers." (PMID 25184276, 2014). "We have shown that loss of WISP2 expression in breast cancer cells leads to acquisition of the CD44+/CD24− phenotype, ALDH+ expression, upregulation of the ABCC2 drug efflux pump expression known to be associated with less differentiated cells and stem cells, although they lack SP cells." (PMID 24498388, 2014). "CD44 resides in lipid rafts, organisation centres for molecules that play key roles in cell migration and whose altered functional behaviour has been implicated in diseases including breast cancer." (PMID 24512624, 2014). "The CD44+/CD24− marker status has been associated with breast cancer stem cell-phenotype." (PMID 25348805, 2014). "Because CD44 is involved in a wide spectrum of physiological functions, its dysregulation has been implicated in progression of a variety of cancers, including breast cancer." (PMID 24512624, 2014). "In breast cancer, these cells were found to be associated with CD44+CD24-low and ALDH+ phenotype." (PMID 23883436, 2013). "In addition genetic variants of CD44 were found to be associated with breast cancer patient survival, risk prediction and prognosis." (PMID 23940692, 2013). "Therefore, one taggerSNP (rs353639) in the CD44 gene of GIH population was selected to evaluate the effect on breast cancer risk." (PMID 23940692, 2013). "Although Notch has been previously implicated in breast cancer stem cell self-renewal the CD44+CD24neg T-ISC sub-population was unaffected by Notch inhibition in 2D culture, sphere and xenograft assays, revealing a heretofore unappreciated heterogeneity in GSI responsiveness in T-ISC." (PMID 23982961, 2013). "CD44 variable exons show variant splicing inclusion in breast cancer cells." (PMID 23935626, 2013). "In this study, we sought to determine genetic variants of CD44 that may confer individual’s risk to breast cancer in 258 patients and 131 healthy controls." (PMID 23940692, 2013). "CD44, an alternatively spliced transmembrane protein, functions as a receptor for hyaluronan and as a co-receptor for multiple receptor kinases that have been linked to breast cancer." (PMID 24324613, 2013). "Therefore, we aimed to investigate the role of CD44 gene polymorphisms in breast cancer risk and prognosis in North Indian population." (PMID 23940692, 2013). "Therefore, the present study was carried out to evaluate the role of CD44 gene polymorphisms in north Indian breast cancer patients." (PMID 23940692, 2013). "In another study with canine cancer cell lines (osteosarcoma, melanoma, glioma and mammary tumor), CD44 expression was associated with proliferation, but the authors concluded that the transient and fluctuating expression may limit its utility as a CSC marker." (PMID 24119896, 2013). "Although we have found that CD44 rs13347 variant genotypes (CT+TT) were associated with increased risk for breast cancer, our study may have certain limitations caused by the study design." (PMID 22788972, 2012). "However, in contrast, it has been recently described that high levels of CD44 in clinical breast cancer are associated with a more favourable prognosis." (PMID 23039365, 2012). "Also, some studies reported strong association between CD44 expression and breast cancer aggressiveness." (PMID 22788972, 2012). "Our results obtained by analyzing 1,853 breast cancer patients and 1,992 controls from two study centers showed that the functional variation rs13347 T in the CD44 was associated with increased risk for developing breast cancer and yields lower five-year survival probability." (PMID 22788972, 2012).
breast carcinoma (continued). "In addition to other reports on CD44 as an EOC TIC marker, the role of CD44 in regulating a TIC phenotype was recently shown when shRNA-mediated knockdown of CD44 caused breast cancer TICs to differentiate and abolished their tumorigenicity in mice." (PMID 22901285, 2012). "The risk of breast cancer related to CD44 rs13347 genotypes were further examined with stratification by age, age at menarche, menstrual history, BMI and family history of breast cancer, pathological type, clinical stage, estrogen receptor status and progesterone receptor status." (PMID 22788972, 2012). "CD44 expression has also been associated with stem-like breast cancer cells." (PMID 22937154, 2012). "In addition, the ability to secrete PGE2 associates with the ability to expand CD44+/CD24−/EpCAM+ breast cancer cells." (PMID 21957456, 2011). "In addition, an association between basal-like breast cancer and the presence of CD44+/CD24− cells has been established." (PMID 20585577, 2010). "Paired breast cancer core biopsies obtained from patients with primary breast cancer before and after 12 weeks of chemotherapy found that chemotherapy caused a 3-fold increase in the CD44+/CD24-/low breast CSC population." (PMID 20979639, 2010). "Moreover, a high CD44 low CD24 expression profile in breast cancer cell lines has been associated with a putative breast cancer initiating cell phenotype." (PMID 20591176, 2010). "The role of the various known CD44 variants in breast cancer is a matter of debate." (PMID 19602265, 2009). "More specifically, SFRS10 is significantly overexpressed in breast cancer and might be responsible for splicing of CD44 isoforms associated with tumor progression and metastasis." (PMID 19014521, 2008). "Herrera-Gayol and Jothy showed that CD44 variants (especially CD44v6) could regulate the binding of breast cancer cells to extracellular HA, and these binding interactions could mediate tumor cell metastasis." (PMID 18350162, 2008). "Association of CD44/CD24 phenotypes with breast cancer subgroups." (PMID 18559090, 2008). "CD44 associates with MMP- 9 on the cell surface of mammary carcinoma and melanoma cells." (PMID 17343740, 2007). "However, some studies indicate an association of CD44v with the luminal A subtype of breast cancer, which generally has a better prognosis, while the CD44 variant v3–10 has shown superior effectiveness compared to the standard isoform in slowing tumor growth and metastasis." (PMID 40563429, 2025). "To address the possible mechanism of chemoresistance mediated by RHAMM, we examined the expression of CD44, another receptor of HA and representative marker of breast cancer stem cells (CSCs), because CSCs are closely associated with chemoresistance of human malignancies, including breast cancer." (PMID 39518040, 2024). "However, the observed DS variant-triggered alterations in the actin cytoskeleton of breast cancer cells may also result from the interaction of these glycans with CD44, which is an another adhesion molecule." (PMID 39062543, 2024). "Moreover, in immunostained paraffin tissue sections of breast cancer, a CD44-associated pericellular HA matrix has been observed on tumour emboli invading such lymphatic vessels, while in vitro cultured breast tumour lines have been reported to adhere via HA to LYVE-1 in transfected fibroblasts." (PMID 37606814, 2024). "However, although several splicing factors modulating CD44v have been identified, the mechanism underlying CD44 AS, especially CD44v8-10 AS, in breast cancer remains unclear." (PMID 35504883, 2022). "Furthermore, we further analysis the correlation of risk score and immune checkpoint in breast cancer and demonstrated that most of key checkpoint were significantly differentially expressed between the two groups in breast cancer patients, including CD44, TIGIT, CTLA4, CD274, CD86 and CD80." (PMID 35052427, 2021).
breast carcinoma (continued). "Although both GRP78 and CD44 have been widely implicated in aggressive cancer growth and therapeutic resistance, the physical and functional interactions of these two proteins in the context of breast cancer cells resistant to hormonal treatment are just emerging." (PMID 31416894, 2019). "Expression of CD44 is upregulated in premalignant lesions and is associated with particular cancer types, including prostate cancer, head and neck squamous-cell carcinoma, central nervous system malignancies, respiratory track malignancies, melanoma and breast cancer." (PMID 29190904, 2017). "Expression of the epithelial CD44 variant containing exons v8-10 (CD44v8-10) has been associated with more chemoresistant and metastatic tumors in gastrointestinal and breast cancers, but its role in ovarian cancer is unknown; we therefore investigated its use as a prognostic marker in this disease." (PMID 27253518, 2016). "Therefore, targeting AF1q/TCF7/CD44 regulatory axis and its associated signaling molecules of the Wnt pathway may be a useful therapeutic strategy for breast cancer patients." (PMID 26079538, 2015). "Therefore, reasons for discrepancy in the effect of CD44 polymorphisms on breast cancer susceptibility may be because these polymorphisms have indirect role on breast cancer susceptibility." (PMID 23940692, 2013). "However, in view of limited studies, we aimed to determine the association of previously significant reported SNP (rs13347), together with taggerSNP (rs353639) in the CD44 gene of Hapmap- GIH population with breast cancer risk and prognosis in North Indian population." (PMID 23940692, 2013). "Consequently, nuclear β-catenin and upregulation of CD44 may be potential diagnostic and therapeutic targets for breast cancer metastasis." (PMID 20696077, 2010). "For instance, DDX17 promotes EMT in breast cancer by modulating alternative splicing of CD44, thereby enhancing metastatic potential." (PMID 41367298, 2026). "Apt1-modified liposomes successfully delivered DOX to CD44-positive breast cancer cells while maintaining low systemic toxicity." (PMID 41560835, 2026). "Elevated CD44 expression correlates with increased tumor burden, enhanced distant metastasis, and reduced survival rates, providing clinical evidence that CD44-positive breast cancers are more prone to recurrence and distant spread." (PMID 41596432, 2026). "CD44 is a transmembrane glycoprotein that is frequently expressed on stem-like breast cancer cells, which can be detected in the bone marrow of patients with early-stage breast cancer." (PMID 41596432, 2026). "The confinement‐induced emergence of CD44+ CD133+ breast cancer cell populations was still observed in peripheral regions of cancer spheroids after pharmacological inhibition of ROCK, myosin II, and YAP." (PMID 40569213, 2025). "Research shows that irradiation or EMT upregulates stemness markers, increasing CD24−/low/CD44+ cell populations indicative of CSCs, as observed in breast cancer." (PMID 40363706, 2025). "While the exact origin of cancer stem cells (CSCs) remains elusive, biomarkers for breast cancer stem cells (BCSCs) have been identified, such as CD44+ve/CD24−ve/low cells that exhibit aggressive behavior and drug resistance." (PMID 39858015, 2025). "To examine the stem features of the different breast cancer cell lines, we assessed the expression of CD44, CD24 and ALDH1 in both MCF-7 and MDA-MB-231 cell lines using FACS." (PMID 39955575, 2025). "CD44 also accounts for increased resistance to doxorubicin in breast cancer and sunitinib in clear cell renal cell carcinoma." (PMID 41168417, 2025).
breast carcinoma (continued). "Using the well-established epithelial CD104 (β4 integrin) and mesenchymal CD44 cell surface markers, we isolated E/M and M cells from basal-like breast cancer cell lines." (PMID 40764669, 2025). "We analyzed the distribution of systematic reviews and meta-analyses on cell-expressed CD44 from 1995 to 2022, and the data indicate a research emphasis on gastric and breast cancers, which together accounted for more than 1/3 of all studies." (PMID 41440277, 2025). "For instance, the HMLER breast cancer cell line, which naturally overexpresses CD44, was treated with low-dose paclitaxel (10 nM for four days), leading to a subpopulation enriched in CD44+ cells (>30%), termed HMLER fiscal cells." (PMID 40733139, 2025). "LUCAT1 is overexpressed in the BCSC population (CD44+/CD24-) compared to the bulk of the breast cancer cells." (PMID 41181715, 2025). "In breast cancer, switching from oxidative phosphorylation to glycolysis fosters the CD44+/CD24low/EPCAM+ basal-like CSC phenotype." (PMID 40363706, 2025). "For instance, transplantation into CD44+/CD24−/ALDH1+ CSCs from breast cancer into mouse mammary fat pads resulted in the formation of foci that closely resembled the histological features of the primary tumour." (PMID 40665579, 2025). "Cell assays showed minimal cytotoxicity in MD-MB-231 breast cancer cells and confirmed CD44-mediated targeting, validated by an HA competition experiment." (PMID 41304734, 2025). "Further studies demonstrated that an Os (II) complex with a dca ligand also eradicated CSCs in MCF-7 and SKBR-3 human breast cancer cells, targeting CD44-positive, CD24-negative CSC-like cells and inhibiting mammosphere formation." (PMID 40733139, 2025). "CD44 is also known to modulate proliferation of numerous cell types, including breast cancer cells, lung cancer cells, and epithelial cells." (PMID 41282250, 2025). "We found a correlation in breast cancer between CD44 and BRCA1, although it was a weak correlation with strong statistical significance." (PMID 41373491, 2025). "Incontrast, CD44 peptide-modified AKPC-siYT showed specific targetingto both engrafted breast cancer cells, as observed by the appearanceof a color change." (PMID 40176316, 2025). "The integral cellular glycoprotein and hyaluronic acid receptor CD44 plays an important role in this process and is related to breast cancer malignancy." (PMID 40806710, 2025). "Over the last few years, several preclinical studies have also been conducted in which various monoclonal antibodies against CD44 and CD44v6 were investigated in pancreatic cancer, acute myeloid leukaemia, breast cancer and chronic lymphocytic leukaemia." (PMID 41168417, 2025). "The disruption of the dimeric interface has been reported to impair the CD44 exon v5 splicing in a human breast cancer cell line stably transfected with a CD44 minigene system." (PMID 39858525, 2025). "CD44+CD24−/low cells account for 11%–35% of breast cancer cells, suggesting that they are a small but essential subpopulation of stem cells responsible for maintaining tumour heterogeneity and treatment resistance." (PMID 40665579, 2025). "Since the discovery of cancer stem cells (CSCs) in solid tumors, CD44 has been widely used as a CSC marker in breast cancer and other malignancies." (PMID 40046628, 2025). "The most consistently used biomarkers for identifying breast cancer stem cells (BCSC) are CD44, CD24, and ALDH1." (PMID 40707430, 2025). "Breast cancer spheroids exhibited enriched CSC populations (CD44+/CD24-) after treatment with a HER2 inhibitor, reflecting therapy-induced stem cell formation." (PMID 41050078, 2025). "Using correlative light and electron microscopy imaging to detect HA, HAS3, and CD44, melanoma-derived EVs of various sizes were visualized while attached to the surface of normal human keratinocytes and breast cancer cells in vitro." (PMID 39851567, 2025).
breast carcinoma (continued). "These validated that LNPsmodified with a CD44-specific peptide mediate highly efficient targetingto CD44+ breast cancer cells." (PMID 40176316, 2025). "In breast cancer tissues, high expression of CD44+/CD24- can increase the invasiveness of breast cancer cells and promote tumor recurrence and distant metastasis." (PMID 41019994, 2025). "Our previous study identified that ESA+CD44+CD24-/low breast cancer cells have stem-like cell characteristics." (PMID 39991565, 2025). "Another weak correlation was found in the case of breast cancer, between CD44 and BRCA1 (r = 0.5; p = 0.02)." (PMID 41373491, 2025). "IM7, another anti-mouse/human pan-CD44 IgG2b mAb that recognizes the HA-binding domain of CD44, inhibits the cell migration and invasion of breast cancer cells." (PMID 41011286, 2025). "Taken together, these observations verified a key link between physical confinement and the emergence of a drug‐resistant CD44+ CD133+ breast cancer cell population at the cancer spheroid peripheries." (PMID 40569213, 2025). "Concordant with functional experiments, SGK3 overexpression led to elevated expression of stem cell marker CD44 and c-Myc in breast cancer cells." (PMID 40303291, 2025). "ESRP1, by regulating the expression of CD44 splice variants, can influence the behavior of tumor cells, significantly impacting the EMT process and breast cancer metastasis." (PMID 40046628, 2025). "In breast cancer, for instance, CSCs are commonly identified by the markers CD44+/CD24−/low and ALDH+ (aldehyde dehydrogenase), which are associated with their ability to initiate tumor formation and sustain tumor growth." (PMID 39941751, 2025). "For example, studies have shown that the Hedgehog pathway contributes to self-renewal and preservation of CSC populations, such as the CD44+CD24−/low subset in breast cancer, through mechanisms involving regulation of key genes such as BMI-1." (PMID 40430852, 2025). "CSC markers associated with breast cancer, such as CD133, ALDH1, and CD44+/CD24-, are positively correlated with angiogenic mimicry and the molecules involved in vasculogenic mimicry formation." (PMID 41368628, 2025). "To investigate TCF1 inputs into partial EMT (p-EMT), we FACS-sorted E/M and M cells from the MDA-MB-468 basal-like breast cancer cell line using CD104/CD44 differential surface expression." (PMID 40764669, 2025). "The expression level of CD44 in 4T1 breast cancer cells was substantially higher than that in undifferentiated bone marrow-derived macrophages (M0-BMDMs), naive CD8+ T cells, and activated CD8+ T cells." (PMID 40593710, 2025). "CSCs exhibit unique surface markers (e.g., CD44 + /CD24 − /low in breast cancer, CD44 + /CD133 + in prostate cancer) and upregulated signaling pathways like Hedgehog-Gli1 and TGFβ1 that are minimally active in normal progenitors." (PMID 40690143, 2025). "To confirm the stemness and immunomodulation markers expression on mouse breast cancer cell lines, we analyzed the expression of CD44 and CD274 (PD-L1) with flow cytometry in two cell lines, EO771 and 4T1." (PMID 40160820, 2025). "Previous studies have shown that breast cancer cells contain stem-cell-like cells that express CD44+CD24-/low marker, and compared to non-CD44+CD24-/low cancer cells, these cells possess more than 50-fold increased tumorigenic capacity." (PMID 39991585, 2025). "DNA aptamers that specifically bind to CD44 exon v10 were selected via SELEX to inhibit breast cancer cell migration." (PMID 41440277, 2025). "Quercetin enhanced the doxorubicine effect in T47D and its CD44+/CD24− breast cancer cell line through cell cycle arrest and increased apoptosis." (PMID 39859345, 2025). "In summary, compared with unmodified MC3-siYT,CD44 peptide-modifiedAKPC-siYT induced enhanced gene silencing and antitumor efficacy inzebrafish breast cancer cell xenografts with a good safety profile." (PMID 40176316, 2025).